IL13 (interleukin 13)
Diseases named in the same sentence as IL13 in open-access papers (continued):
Sharing a sentence is not in itself a finding about the gene and the disease.
asthma (continued). "Furthermore, in patients with T2-high asthma, such a complex process may result in IgE, IL-13, IL-4, IL-5, and eosinophil responses, covering more than 50% of asthma endotypes." (PMID 38203353, 2023). "Hence, the efficacy of dupilumab in inhibiting the pathobiologic mechanisms underlying type 2 inflammation, strongly dependent on IL-4 and IL-13 actions, explains the extension of the therapeutic effects of this monoclonal antibody to both asthma and nasal polyposis in our patients." (PMID 37063895, 2023). "Importantly, the administration of the NOD1 ligand promoted significant changes in all the hallmarks of asthma models including increased AHR and eosinophil recruitment, higher levels of seric specific IgE and IL13 production among other asthma-related mediators." (PMID 36189256, 2022). "Furthermore, curcumin-SLN reduced airway hyperresponsiveness and inflammatory cell infiltration, as well as the lower production of cytokines, including interleukin-4 and interleukin-13, indicating that it may be useful in the treatment of asthma." (PMID 35455087, 2022). "Therefore, in this review, the IL-4/IL-13 signaling pathways and therapeutic monoclonal antibodies targeting each cytokine or their receptors, as well as dual IL-4/IL-13 blockade, in both AR and asthma are presented and discussed." (PMID 35663523, 2022). "In the OVA and IL-33-treated asthma mouse model, enhanced activated macrophage differentiation is induced in females compared with that in male mice, along with a mechanism dependent on IL-13 production and the signal transducer and activator of transcription 6 activation." (PMID 35625578, 2022). "IL-13 plays a key role in many pathological processes, such as asthma, pulmonary fibrosis, and ulcerative colitis, and IL13 as an inflammatory factor plays an important part in various inflammatory reactions, suggesting IL13RA2 may play an important role in PVR." (PMID 35770008, 2022). "EoE shares several commonalities with asthma, including aberrant eosinophil activation and recruitment, the prominence of IL-13 and epithelial dysfunction, and overlapping therapeutic targets such as the IL-4 receptor, IL-13, thymic stromal lymphopoietin, IL-5, and IL-5R." (PMID 35082127, 2022). "Additionally, there are other cytokines which could be targeted for asthma, namely IL-4 and IL-13 and whilst there has been some study in this area, only one IL-4 inhibitor has been approved for asthma treatment (Dupilumab)." (PMID 36232470, 2022). "In asthma, Naive T lymphocytes are inadequately prepared to respond to inhaled aeroallergens with Th2 polarity, and upon restimulation by inhaled aeroallergens, they produce Th2 cytokines, IL-4, IL-5 and IL-13, that promote the pathological mechanisms of asthma." (PMID 35745177, 2022). "After stimulation by interleukin-13 (IL-13), goblet cell proliferation, high secretion of selective cytokines, and increased recruitment of neutrophils could be observed in the chip, successfully realizing the simulation of the pathological state of asthma." (PMID 34577749, 2021). "Another limitation of using gene expression profiling of selected cytokines (IL4, IL5, and IL13) in induced sputum for asthma stratification in comparison to unsupervised approaches employing several biomarkers is that prevalence of T2-high asthma might be underestimated." (PMID 33513844, 2021). "Indeed, further studies that aim to assess the impact of different mAbs on specific asthma phenotypes according to the levels of IgE, IL-4, IL-5, and IL-13 may further optimize the efficacy of the current mAbs for the treatment of severe asthma." (PMID 34281184, 2021). "In mice, ORMDL3 expression has been shown to be induced by allergen, IL-4 and IL-13 via STAT6 and in bronchial epithelial cells, overexpression of ORMDL3 has been shown to trigger activating transcription factor 6 (ATF6), which has also been implicated in airway remodeling in asthma." (PMID 35386986, 2021).
asthma (continued). "Thus, we speculate that combined blockade of IL-4 and IL-13 pathways is probably also required in order to efficiently reduce most features of asthma in human, as we observed here in mouse models with the IL-4 and IL-13 vaccines." (PMID 33976140, 2021). "Interestingly, the increased smooth muscles in asthma might be a major source of pro-inflammatory asthma-relevant cytokines such as IL-13, IL-17, IL-22, IL-33, lymphopoietin, semaphorins, and CXC chemokines." (PMID 34834581, 2021). "Dupilumab, blocking IL-4 and Il-13 from binding to its receptors, was the first biologic approved for moderate to severe AD, and Omalizumb, anti- IgE monoclonal antibody, was the first biologic approved for the treatment of asthma in the Unated States and the European Union." (PMID 34911576, 2021). "In asthma, after activation by epithelial-derived alarm cytokines, ILC2s promote pulmonary inflammation by secreting type 2 cytokines, including IL-4, IL-5, and IL-13, to enhance the contraction of smooth muscle, secretion of mucus, and infiltration of inflammatory cells." (PMID 34177881, 2021). "Allergic asthma is the most common asthma phenotype, and Th2 immunity is classically thought to be important in mediating bronchial inflammation during allergic asthma by cytokines such as IL-4, IL-5, and IL-13 produced from CD4 + Th2 cells and innate lymphoid cells." (PMID 34194525, 2021). "Similarly, IL-13 can induce cytoprotective cytokines such as vascular endothelial growth factor to protect from acute lung injury, yet drive airway smooth muscle cell contraction leading to broncho-constrictive effects during asthma pathogenesis." (PMID 34127548, 2021). "Finally, asthma-related Th2 cytokines such as IL-4, IL-5, and IL-13 can induce EGFR expression, while cytokines produced by activated eosinophils such as IL-3 and IL-5 can induce TGF-α production by epithelial cells and subsequently induce mucins production through EGFR signaling." (PMID 34248677, 2021). "Thus IL‐13 and CCL5 may be associated with asthma exacerbation, although this relationship remains unclear." (PMID 33534941, 2021). "Thus, formoterol enhanced IL13-induced asthma features, while nadolol reduced them, suggesting a role for β2-adrenergic signaling in the development of asthma epithelial abnormalities, as corroborated in ovalbumin-challenged mice displaying worsened airway hyperresponsiveness." (PMID 34248677, 2021). "This is consistent with our results suggesting that Fbp1 may be involved in the pathogenesis of asthma and that its elevated level in epithelial cells following ovalbumin challenge or IL‐4 or IL‐13 treatment may be a detrimental mechanism inducing injury in bronchial epithelial cells." (PMID 33960626, 2021). "Thus, ruxolitinib may regulate the allergic reaction induced by TLRs and IL‐13 in the airway cells, leading to asthma remission." (PMID 33534941, 2021). "Since the inflammation mediator and remodeling trigger, IL-13, is known to play a central role in the pathophysiology of asthma, this study was aimed to identify novel IL-13-regulated epigenetic modifiers in asthma that may contribute to subepithelial fibrosis." (PMID 33688506, 2021). "In the three treated groups of asthma and also, allergic rhinitis (Co-Q10 received groups, Co-Q10 and O-3 received groups, Co-Q10 and Mg-S received groups), reverse trend was found and significantly reduced IL-4, IL-5, IL-13, and restored the IFN-γ levels (P < 0.05)." (PMID 33743807, 2021). "This steroid unresponsive source of IL13 is associated with BAL neutrophilia and bacterial dysbiosis, highlighting the importance of a greater understanding of the innate and adaptive immune responses in the peripheral airways of severe asthma and how they relate to clinical disease expression." (PMID 33411348, 2021). "Therefore, increased levels of IL-13, IL-5, and IL-4 mediate the development of asthma." (PMID 34258300, 2021).
asthma (continued). "Indeed, several studies support the notion that IL-13 is the major effector molecule in asthma." (PMID 32477356, 2020). "Thus, PM may induce autophagy through the response to IL-13 promoting TGF-b1 airway remodeling and the loss of lung function in asthma." (PMID 32411804, 2020). "However, unlike IL-13 and IL-5, which are increased in individuals with asthma, COX-2 deficiency has been linked to increased severity of asthma progression." (PMID 33022979, 2020). "Our data suggest that IL–13 may play a dual role in severe asthma: on the one hand driving pathologic corticosteroid‐refractory mixed granulocytic inflammation, but on the other hand underpinning beneficial epithelial repair responses, which may confound responses in clinical trials." (PMID 32096290, 2020). "The classical form of asthma is considered to be mediated by T helper cell type 2 (Th2) cells and is characterized by eosinophilic inflammation, immunoglobulin (Ig) E reactivity, and the predominance of Th2 cytokines such as interleukin (IL)-4, IL-5, and IL-13." (PMID 32580518, 2020). "Asthma is classically considered an IgE-mediated, lymphocyte T helper 2 (Th2)-associated pathology, with an allergic inflammatory infiltrate characterized by eosinophils, mast cells, and CD4+ T cells producing interleukin-4 (IL-4), IL-5, and IL-13 in the airways." (PMID 33324573, 2020). "In addition, the number of IL-13+ ILC2 was reported to be markedly upregulated in patients with uncontrolled asthma, and it was significantly decreased when these patients had their symptoms controlled by treatment, suggesting an important role for ILC2-derived IL-13 in asthma." (PMID 33193374, 2020). "IL-13 may therefore contribute to goblet cell hyperplasia in both asthma and COPD." (PMID 31664154, 2019). "Many studies confirmed that a broad spectrum of inflammatory mediators, such as IL-4, IL-5, and IL-13, synthesized and released by activated inflammatory cells, particularly Th2 cells, eventually induce airway mucus hypersecretion which is essential for the pathogenesis of asthma." (PMID 31073274, 2019). "Therefore, it is hypothesized that anti-IL-4 and anti-IL-13 therapies could decrease asthma exacerbation by inhibiting eosinophilic and airway inflammation." (PMID 31151443, 2019). "Therefore, patients may benefit more from combined blocking of IL-4 and IL-13 with monoclonal antibodies because of the overlapping pathophysiological roles of IL-13/IL-4 in asthma." (PMID 30703143, 2019). "However, these Abs have not shown any favorable therapeutic benefits in clinical trials for asthma, suggesting that blocking IL-4 or IL-13 alone might be insufficient because of the redundancy in their signaling pathways." (PMID 31123339, 2019). "The evidence of IL-25-mediated Th2 cell differentiation, increase in production of IL-4, IL-5, and IL-13, elevated IgE and IgG levels, eosinophil infiltration, goblet cell hyperplasia and mucus hypersecretion, provided the proof for the role of IL-25 into asthma pathogenesis." (PMID 31355170, 2019). "Th2-cell derived cytokines including IL-4, IL-5, and IL-13 could contribute to long-term airway hyper-responsiveness and smooth muscle growth, which have significant impact on the decline of lung function and the development of asthma severity." (PMID 30691461, 2019). "Meanwhile, IL-13 reportedly promoted the differentiation of naïve T-cells to Th2 cells, activating isotype switching toward IgE production in allergen-specific B-cells, contributed to mucous metaplasia, and enhanced the remodeling of airway walls in patients with asthma." (PMID 31861989, 2019). "Moreover, IL-37b could significantly suppress the induced concentrations of Th2 and asthma-related cytokines IL-4, IL-6, and IL-13 in lung homogenate of asthmatic human PBMC NOD/SCID mice (all P < 0.05)." (PMID 29988381, 2018).
asthma (continued). "This type of asthma is thought to arise from an imbalance in T helper type I (Th1)-Th2 immune regulation, resulting in increased levels of the Th2 cytokines interleukin (IL)-4, IL-5, and IL-13, which have been proven to be important drivers of allergic airway inflammation in asthma." (PMID 29867963, 2018). "Finally, it might be interesting to evaluate its application to common diseases where IL-13 signalling through both receptors plays a critical role, such as asthma and/or atopic dermatitis." (PMID 30318506, 2018). "To clarify the underlying mechanism of how IL-4 and/or IL-13 generates asthma-like phenotypes by acting on airway epithelial cells, we studied IL-4/IL-13–inducible genes in those cells using a DNA microarray and found that SCCA1 and SCCA2 are downstream molecules of IL-4/IL-13." (PMID 29642409, 2018). "Interestingly, the healthy control subjects had significantly higher IL‐13 in their serum as compared to the severe asthmatics (P = .0002), whilst conversely, asthma patients had higher levels of IL‐6 and IL‐8 as compared to the healthy controls (both P < .0001)." (PMID 29130617, 2018). "Therefore, the incidence of IL-13+ ILC2s may provide us with a surrogate marker of the inflammatory status of the disease, and the physiological function of IL13+ ILC2 among asthma patients with distinct clinical characteristic should be further investigated." (PMID 29449864, 2018). "Significantly, production of IL-5 and IL-13 is 100- to 200-fold greater in ILC2 cells compared to CD4+ T cells suggesting that IL-33-dependent activation of ILC2 cells during RV infection could play a major role in the development of asthma." (PMID 29915592, 2018). "However, they confirmed that dupilumab, a medication simultaneously targeting at both IL-4 and IL-13 via blocking IL-4 receptor, has yielded more consistent results in reducing asthma exacerbations and improving lung function, especially in patients with increased blood eosinophils." (PMID 30050954, 2018). "Thus, these miRs may be used in the future as biomarkers or therapeutic targets to restore or block the IL-13 signalling in diseases such as asthma, atopic dermatitis, eosinophilic esophagitis and UC." (PMID 29438285, 2018). "IL-13 has long been thought to have pleiotropic effects in immune pathology in asthma, and its role in CRS, including induction of goblet hyperplasia, epithelial mesenchymal transformation, fibrosis, affecting tight junction formation and chemokine induction, may be similar." (PMID 29707206, 2018). "Consistent with this hypothesis, clinical trials of monoclonal antibodies to IL-13 or its receptor in patients with asthma have consistently shown increases in peripheral blood eosinophil counts, and tissue eosinophilia was decreased in a recent phase 2 study of anti–IL-13 antibody in EoE49." (PMID 28751971, 2017). "IL-13 is well known to be a key factor for the development of allergic disease and asthma and, therefore, changes in concentrations of this cytokine are likely influenced by factors other than age and may explain the lacking decrease even in the non-atopic Australian population." (PMID 29312902, 2017). "Likewise, IL-13 was identified as a target of let-7 in an IL-13-dependent murine model of asthma." (PMID 27187364, 2016). "IL-13 is a key Th2 cytokine that might be involved in the development of asthma." (PMID 27134644, 2016). "Indeed, anti-TNF-α therapy has been reported to reduce the expression of MMP-9 as well as that of other inflammatory cytokines (e.g., IL-4, IL-13, and IgE), thereby hindering the recruitment of inflammatory cells and inhibiting the airway inflammation in asthma." (PMID 26783416, 2016). "Airway inflammation is essential to the pathogenesis of asthma and is triggered by respiratory viral infections and inhaled allergen, leading to the activation of T helper 2 (Th2) cell differentiation and the secretion of Th2 cytokines such as IL-4, IL-5, and IL-13." (PMID 27274620, 2016).
asthma (continued). "Recently, asthma endotype cluster analysis followed by genotype or phenotype cluster analysis has achieved successful clinical results, including anti-IL-5 antibody therapy for persistent eosinophilic severe asthma and anti- IL-4 or anti-IL-13 antibody therapy for high-Th2-type severe asthma." (PMID 27965774, 2016). "Cytokines other than IL-4 and IL-13 may be responsible for increases in pendrin expression; IL-1β, a macrophage-secreted cytokine involved in the immunopathogenesis of asthma and COPD, has also been shown to increase pendrin levels in rodent and human bronchial epithelial cells." (PMID 26612971, 2015). "It has long been known that asthma is a disease linked to the activation of helper Th2-lymphocytes (whose key cytokines are mainly IL-2, IL-3, IL-4, IL-5, IL-9, IL-13 and GM-CSF) with a concomitant lack of inhibition by Treg lymphocytes for defective production of IL-10." (PMID 25671117, 2015). "In addition, oral administration of curine significantly inhibited eosinophil recruitment and activation, as well as, OVA-induced airway hyper-responsiveness in a mouse model of asthma, through inhibition of the production of IL-13 and eotaxin, and of Ca2+ influx." (PMID 25781071, 2015). "Furthermore, several reports showed that Th2 cytokines, particularly IL-4 and IL-13, laid at the center of the recruitment of eosinophils and promoting goblet cell metaplasia and hyperplasia, leading to airway mucus hyper-secretion in asthma." (PMID 26343632, 2015). "Further, we have shown that, although a variety of Th2 cytokines as well as IL-25 have been implicated in causing remodelling changes in human and murine airways in asthma, only IL-25, and not IL-4, IL-5 or IL-13 is able directly to induce angiogenesis by human vascular endothelial cells." (PMID 25889697, 2015). "We hypothesized that interactions between genetic variants and methylation in genes in this pathway (IL4, IL4R, IL13, GATA3, and STAT6) influence asthma risk, that such influences are age-dependent, and that methylation of some CpG sites changes over time in accordance with asthma transition." (PMID 24735657, 2014). "Interleukin 13 is induced by CHIA, variations of which may lead to asthma susceptibility." (PMID 25372592, 2014). "IL-13 and IL-10 responses were not independently associated with asthma, eczema or atopy." (PMID 24875149, 2014). "Moreover, an increase in the airway hyperresponsiveness of asthma and airway remodeling may be due to increased production of IL-4, IL-5, IL-6, and IL-13 in the inflammated airways." (PMID 23533467, 2013). "Therefore, a good example is the IL-4 and IL-13 pathway for anti cytokine treatment against asthma." (PMID 24032029, 2013). "AHR is also an important pathological symptom in asthma patients, and IL-13 may enhance AHR." (PMID 23049614, 2012). "The anti-IL-13 mAb lebrikizumab (Genentech/Chugai Pharmaceutical) has recently been demonstrated to significantly improve lung function in patients with inadequately controlled asthma, but only in a subgroup defined on the basis of high serum levels of periostin." (PMID 23189057, 2012). "Periostin exhibits effects on epithelial cells and fibroblasts that may contribute to airway remodeling in asthma and may prove to be useful as a biomarker to identify those subjects most likely to give a positive clinical response to IL-13 antagonism." (PMID 23189057, 2012). "The suppression of all the symptoms of asthma in the present study was associated with reduced levels of various Th1 cytokines (TNF-α, IL-6, and IL-1β), with reduced levels of various Th2 cytokines (IL-4, IL-5 and IL13) and with reduced levels of a Th17 cytokines (IL-17F) in splenocytes." (PMID 23346203, 2012). "Moreover, it is well established that there is a strong interaction between eosinophils and Th2 cells in the asthmatic airways and that Th2 cell-derived cytokines, namely IL-4, IL-5, and IL-13, play critical roles in orchestrating and amplifying allergic inflammation in asthma." (PMID 21772663, 2011).